AHR (aryl hydrocarbon receptor)
Diseases named in the same sentence as AHR in open-access papers (continued):
Sharing a sentence is not in itself a finding about the gene and the disease.
cancer (continued). "Characterizing this phenomenon remains an important aspect of the involvement of the AHR in regulating metabolism given the clinical potential of the AHR-FGF21 regulatory axis not only in metabolism, but also in other diseases such as cancer." (PMID 33374508, 2020). "Therefore, the administration of AhR antagonists, both in combination with chemotherapy and within a balanced diet, could combine the containment of inflammation with common cytostatic therapies that are used to fight this type of cancer." (PMID 32722276, 2020). "By increasing the NAS/melatonin ratio, AhR-induced NAS activates TrkB, which can enhance the survival and proliferation of cancer stem-like cells (CSC)." (PMID 33375613, 2020). "In particular, a Src-mediated crosstalk between AHR and EGFR has been shown to trigger the activation of ERK1/2 and the stimulation of proliferative effects in cancer cells." (PMID 31370872, 2019). "The activated TF AHR can upregulate the expression of target gene DLL4 and activate the Notch signaling pathway, which can lead to tube formation in cancer cells, increase blood vessel branching, reduce pericyte recruitment, and reduce fibronectin expression." (PMID 31126066, 2019). "To provide cellular level evidence of AR‐Qs and AhR interactions, we introduced AhR knockdown in AR‐Qs transfected HEC‐1A cells and measured HEC‐1A cancer cell growth with colony‐formation assay." (PMID 28782227, 2018). "This is consistent with the role of 1MT in cancer immunotherapy, which by inhibition of IDO—or shown here as activating the AHR response—primes the immune system to fight tumors." (PMID 29190885, 2017). "Collectively, these data prove that AHR-expression level is inversely correlated with malignancy, especially EMT, in various cancer cells." (PMID 27752740, 2017). "Among the differentially expressed genes in metastatic samples, we found 7 of 30 genes (MAPK13, XIAP, AHR, SPN, TER1, EMP2, NDUFC2) were cancer-related." (PMID 28009993, 2017). "The aryl hydrocarbon receptor (AHR) plays crucial roles in inflammation, metabolic disorder, and cancer." (PMID 28878246, 2017). "Taken together, these results provide a novel insight into the cross-linking between AhR and autophagy, we addressed the mechanistic BNIP3 modulation by endogenous AhR, which affect cancer cell EMT progression." (PMID 28195146, 2017). "Thus, AHR may be an attractive target with dual effects during cancer treatment." (PMID 27752740, 2017). "Deregulation of AHR and HIF-1α activity can promote various disease states including cancer proliferation, and ARNT has been shown to be essential in supporting these pathophysiological characteristics." (PMID 26909609, 2016). "Consistency between rodent and human bioassays also demonstrates support for a mechanism of carcinogenicity via initial binding to the aryl-hydrocarbon receptor (AhR) by PCB 126 and 2,3,7,8-tetrachlorodibenzo-para-dioxin, (TCDD) in other cancers." (PMID 26425136, 2015). "The cell-autonomous effects of AhR depletion appeared to involve an EMT process and an increased content of cancer stem-like cells." (PMID 26242870, 2015). "ARNT serves as binding partner for several bHLH members and plays a key role in two distinct cellular signalling pathways – the AhR and HIF pathways - activated in response to environment stimulations and also largely involved in cancer cell biology." (PMID 25669983, 2015). "In the current paper, we investigated enantiospecific effects of KET on AhR-CYP1A signaling pathway in cancer cell lines and in human hepatocytes, and we provide the first evidence of enantiospecific interactions of KET with AhR-signaling pathway in vitro." (PMID 25000292, 2014). "As preclinical studies also suggest that the AHR is responsible for mediating – at least in part – the immunosuppressive effects of cancer-derived TRP metabolites, the AHR represents a logical pharmaceutical target for cancer immunotherapy." (PMID 25628622, 2014).
cancer (continued). "Since omeprazole and lansoprazole are activators of aryl hydrocarbon receptor (AhR) and inducers of CYP1A genes, we examined their enantiospecific effects on AhR-CYP1A pathway in human cancer cells and primary human hepatocytes." (PMID 24887303, 2014). "Some signaling pathways, such as notch, CXCL12-CXCR4, Oct4-TCL1-AKT, PTEN/P13K/Akt, β-catenin/Tcf, AhR, and HIF-2α with TGF-β/Smad2 are related to the ABCG2 status as a marker of stem cells or stem-like cancer cells." (PMID 24312054, 2013). "In order to delineate the molecular mechanisms underlying AHR-mediated transrepression we sought to uncouple AHR and ARNT function in ER-positive human cancer cell lines." (PMID 22235307, 2012). "Immunoblot analyses with well-characterised antibodies demonstrated that AhR and CREB were both expressed in all four of the carcinoma cell lines." (PMID 19340314, 2009). "PARP7 inhibitors (PARP7i) and aryl hydrocarbon receptor agonists (AHRa) can synergistically suppress growth of some cancer cell lines but not others." (PMID 41295982, 2026). "Importantly, this has allowed us to answer the long-standing question about the degradation of transcriptionally active AHR and PARP7, both of which are important therapeutic targets in cancer, infections, and immune diseases." (PMID 41326691, 2026). "In addition, PM2.5 exposure induces aryl hydrocarbon receptor (AhR)-dependent transcription of transmembrane serine protease 2 (TMPRSS2) and interleukin-18 (IL-18), further promoting cancer progression in EGFR-mutant cells." (PMID 39578555, 2025). "This AHR/ARNT axis affects several biological processes, including inflammation, allergic responses, metabolism, genetic expression, infectious disease responses, neuronal diseases, cancer, and aging." (PMID 40765830, 2025). "To determine whether the anticancer effects of 7k were mediated through AhR inhibition, we evaluated the expression of AhR downstream targets, including AhR, AhRR, and IDO-1, in kynurenine-stimulated cancer cells using qPCR analysis." (PMID 41155994, 2025). "Increased IDO expression and accumulation of kynurenine can deplete tryptophan, impair effector T and NK cell responses, favor regulatory immune populations and activate Aryl Hydrocarbon Receptor (AHR)-dependent oncogenic signaling, thereby promoting cancer cell survival and proliferation." (PMID 41470122, 2025). "In contrast, the cancer and immune cells in the images on the right exhibit no AhR expression, as indicated by the absence of yellow." (PMID 38680496, 2024). "Moreover, in immune and cancer cells, KYNA is an endogenous agonist of the aryl hydrocarbon receptor (AHR)." (PMID 38969725, 2024). "However, LT-BAY cells exhibited reduced proliferation and migration compared with WT cells, confirming that like other AHR antagonists, BAY2416964 also reduced cancer cell proliferation and migration, but only after long-term treatment." (PMID 39450255, 2024). "Genetic and genomic studies have demonstrated a possible role of AhR in cancer development, where it can act as a positive or negative regulator for carcinogenesis." (PMID 38518996, 2024). "In addition, AhR/CYP1A1 pathway-mediated epigenetic mechanisms play a significant role in regulating gene expression, self-renewal, and the chemoresistance of cancer stem cells in a variety of human malignancies." (PMID 39339278, 2024). "Upon examination of both normal and malignant head and neck tissue samples, H-clustering based on AhR expression revealed that the highest AhR expression was found in these cancer cells, particularly in the nucleus, as opposed to the cytosol." (PMID 38680496, 2024).
cancer (continued). "AhR expression was elevated in the early stages of cancer regardless of cancer type, suggesting that AhR is involved in early events in most cancers." (PMID 38518996, 2024). "It is possible that the developing “I3P pathway” like the Kyn pathway has a nuanced role in cancer with distinct activities not solely dependent on AHR." (PMID 38769298, 2024). "The use of AhR antagonists to enhance ICI therapy has not been tested to date, though AhR antagonists are currently being investigated for their immunomodulatory potential in several cancer types (NCT04069026 and NCT04999202)." (PMID 38459088, 2024). "Expression of AhR and RHOA: Using RT-PCR, we found a correlation between the expression of AhR and RHOA in GCs independently of their subtypes, as previously documented for other types of cancers." (PMID 39200369, 2024). "In primary human hepatocytes and HepG2 cancer cells, it was demonstrated that DMU-212, a tetra-methoxy analog of resveratrol, was the most potent AhR activator and CYP1A1 inducer among 13 different hydroxy- and methoxy stilbenes, including cis- and trans-resveratrol." (PMID 39339278, 2024). "In contrast, the cancer and immune cells in the right images exhibit no AhR expression, as indicated by the absence of yellow regions." (PMID 38680496, 2024). "In contrast, the images on the right depict cancer and immune cells lacking AhR expression, as evidenced by the absence of yellow staining." (PMID 38680496, 2024). "AhR is known to activate several signaling pathways governing proliferation, epithelial–mesenchymal transition (EMT), cell migration, inflammation, immunity, and angiogenesis in cancers." (PMID 39200369, 2024). "In the absence of cancer, AhR activation by the healthy gut microbiome has an important regulatory role in maintaining intestinal homeostasis and gut barrier integrity." (PMID 38448800, 2024). "Conversely, the images on the right depict cancer and immune cells that do not express AhR, as evidenced by the absence of yellow staining." (PMID 38680496, 2024). "Despite AhR not having recurrent genetic abnormalities in most cancer types, its expression is often altered in various types of cancer." (PMID 38518996, 2024). "Ultimately, treating HepG2 cancer cells with Pitavastatin affected significant activation of caspase-3 accompanied by down-regulation of cellular apoptotic biomarkers such as IDO, TDO, STAT3, P21, P27, IL-6, and AhR." (PMID 38653790, 2024). "This is not to say that AHR is never involved in inflammatory responses, which are reported, for instance, in the context of cancer or liver disease." (PMID 39242971, 2024). "It has become clear that AHR activation plays important distinct roles in cancer biology even in the absence of environmental toxins." (PMID 37696456, 2023). "It is reported that cancers expressed high levels of IL4I1, inducing the differentiation of Tregs, promoting CD8+ T cell death, recruiting immunosuppressive TAMs and suppressing T cell proliferation and function via the Kyn-AHR axis." (PMID 37434155, 2023). "Previous studies have shown that IL4I1 could augment growth vitality of cancer cells and diminish the motility of CD8+ T cells through the I3P-aryl hydrocarbon receptor (AHR) axis." (PMID 38250074, 2023). "Several cancers show negative correlation of AHR promoter methylation with HK2 expression, which was associated with worse overall patient survival." (PMID 37696456, 2023). "Similarly, strong AhR inhibitors are used experimentally, but a first-in-humans dose finding study of an AhR inhibitor (BAY2416964) in patients with advanced cancer is in progress." (PMID 37486805, 2023). "Moreover, the level of activation of the AHR and the level of PXR expression were inversely related to the level of proliferation of cancer cells and the stage and grade of cancer." (PMID 37367861, 2023).
cancer (continued). "Although still far-reaching, specific modulation of AhR pathways in TAM and cancer-specific CD8+ T cells by ligands may be considered for future investigation." (PMID 37241719, 2023). "In particular, compared with NCM460 cells, AhR deletion led to death of DLD-1 colonospheres with the increase of passage times likely due to the cytostatic effect on cancer stem cell (not IECs)." (PMID 37781044, 2023). "In multiple different cancer models, the deletion of AhR promotes increased tumorigenesis, but a precise understanding of the molecular cues and the genetic targets of AhR involved in this process is lacking." (PMID 37106727, 2023). "The complex regulatory roles of AHR in normal physiological processes have led researchers to consider the Trp catabolic enzymes as more attractive targets for cancer therapy, rather than directly targeting AHR." (PMID 37655051, 2023). "Compared to VHL, XIAP, and AHR, which were highly expressed in less than half of cancer types in TCGA, PHF14 may serve as a good candidate for pan-cancer usage over co-opted E3 ligases in terms of expression pattern." (PMID 37845222, 2023). "It recognizes structurally diverse exogenous ligands that exhibit their effects on cancer by inducing or inhibiting the canonical, non-canonical, and/or non-genomic AhR pathways." (PMID 37241719, 2023). "It has been demonstrated that the AhR lead agonistic acrylonitrile (Z)-2-(3,4-dichlorophenyl)-3-(1H-pyrrol-2-yl)prop-2-enenitrile (ANI-7) and analogs inhibit proliferation of a broad panel of breast, ovarian and lung cancer cells." (PMID 37241719, 2023). "In addition to the most-commonly altered COSMIC Tier 1 genes, there is a long tail of both cancer-associated and other mutated genes that may play a role in urothelial carcinogenesis and require further investigation; examples include BIRC6, the catalytic arg-200 of GNA13, and Q383H in AHR." (PMID 35655252, 2022). "This apparent discordance between the results of different studies suggests that AHR regulation of basal AKT activity may be cell-type specific and/or reflect differences between primary and cancer cells, a well-known feature of AHR." (PMID 36499247, 2022). "An analysis of the role of AHR in HER2-overexpressing BC cells by performing ATAC-seq using HER2-5 and HER2-5/AHRKO cells suggested that HER2-activated AHR upregulates the expression of genes annotated as “pathways in cancers”." (PMID 36292946, 2022). "The PTGES3′s protein partner subset is enriched with pathway terms such as “protein processing in endoplasmic reticulum”, “pathways in cancer” (KEGG); “cellular responses to external stimuli”, “aryl hydrocarbon receptor signaling” and “TNF alpha Signaling Pathway” (Reactome)." (PMID 35453789, 2022). "Whereas DNA damage in cancer can trigger PARP up-regulation, it is likely that AhR activation will play a major role in enhancing PARP expression and targeting the AhR could be considered a priority approach in cancer therapy." (PMID 36286592, 2022). "Therefore, given this functional circuitry between AhR and IDO1 and their functional relevance to cancer, our studies provide a novel insight into the anticancer efficacy of carbidopa." (PMID 35997090, 2022). "As to whether the AhR-induced CYP1B1 leads to the ‘backward’ conversion of melatonin to NAS, with released NAS activating TrkB on cancer cells and cancer stem-like cells will be important to determine." (PMID 36613754, 2022). "AhR activation by air pollution particular matter elevates heparin-binding EGF-like growth factor (HBEGF) in macrophages, the release of which induces epithelial-to-mesenchymal transition (EMT) in cancer cells, thereby increasing metastasis." (PMID 36613754, 2022). "AHR has been extensively studied in its relationship with CYP1A1 and cancer prevention." (PMID 34262928, 2021). "AhR activation on NK cells and CD8+ T cells leads to a state of ‘exhaustion’, which prevents or suppresses their capacity to eliminate virus-infected cells or cancer cells." (PMID 33562472, 2021).
cancer (continued). "AhR is a ligand-activated transcription factor that belongs to basic-helix-loop-helix (bHLH)/Per-ARNT-Sim (PAS) family, which is involved in the regulation of cell differentiation, proliferation, and cancer imitation." (PMID 34502168, 2021). "In addition, a constitutive expression of IDO in human cancer is sustained by an autocrine signal mediated via STAT-3 activation by proinflammatory cytokine IL-6 and AHR activation by tryptophan catabolites such as kynurenine." (PMID 32384638, 2020). "Not surprisingly, AHR has become a promising target for the treatment of diseases such as autoimmune diseases, inflammation, and cancers." (PMID 32414129, 2020). "As such, the AhR activation as well as extracellular glutamate and ATP may modulate not only NK cell and CD8+ T cell cytotoxicity, but also cancer cell trophic support, via impacts on the cytosolic and mitochondrial melatonergic pathway." (PMID 33375613, 2020). "Some data have revealed that cancer cells can escape immune surveillance by overexpressing TDO2 and activating AhR in a range of cells of both the innate and adaptive immune system—dendritic cells, macrophages, natural killer cells, innate lymphoid cells, cytotoxic T cells and regulatory T cells." (PMID 33542896, 2020). "Is the AhR expressed on chimeric antigen receptor (CAR)-NK cells and does its activation/antagonism modulate the utility of CAR-NK cells in the treatment of an array of different cancers." (PMID 33375613, 2020). "Indeed, other evidence has been presented for an autocrine feedback pathway involving IDO1, AHR, and IL-6 that controls IDO1 expression in cancer cells." (PMID 30254983, 2018). "Previous studies have demonstrated that Notch-AhR-IL-22 axis took part in the pathogenesis of chronic viral infection, however, its role in cancer has not been fully elucidated." (PMID 30473538, 2018). "The results of the present study are of a great relevance to AhR/CSC field, as it provides a better understanding of the regulation of CSCs that may lead to more effective cancer prevention and therapy." (PMID 28103884, 2017). "Targeting IDO inhibition (or AHR activation) in a specifically-transformed cancer cell line simply would not afford the same immunotherapy-relevant insights that we have gained from using MSCs." (PMID 29190885, 2017). "The contradictory observations in AhR-modulated EMT in the context of cancer have not been clarified, particularly for 2,3,7,8-tetrachlorodibenzo-p-dioxin, which is a known human carcinogen as classified by the International Agency for Research on Cancer." (PMID 28195146, 2017). "Herein, our GSEA analyses confirmed that phospho-PRs significantly induce expression of HER2-associated gene sets and demonstrated that phospho-PR target genes also include key mediators of cancer stem cell biology, including PAX, AHR, AR, and RUNX family members." (PMID 28412963, 2017). "This resulted in 97 significantly (FDR < 0.05) overrepresented pathways, including multiple pathways related to TGF-β-, AhR- and NOTCH-signaling, blood coagulation, cell-cell and cell-matrix interactions, as well as pathways related to various diseases such as cancer and heart disease." (PMID 26837704, 2016). "A recent report, which examined the AhR-mediated impact of IDO activation on immunosuppressive functions, such as LPS tolerance and immune escape of cancer cells, offers new insights for a better understanding of the development of cellular dysfunctions in immunoparalysis." (PMID 26881062, 2015). "Here, we hypothesized that the AHR and STAT3 are involved in driving IDO expression in human cancers." (PMID 24657910, 2014).